CXCL1 (C-X-C motif chemokine ligand 1)
Diseases named in the same sentence as CXCL1 in open-access papers (continued):
Sharing a sentence is not in itself a finding about the gene and the disease.
breast carcinoma (continued). "For this reason, this subsection will only discuss the role of CXCL1 in female breast cancer." (PMID 37108425, 2023). "Circulating levels of CXCL1 are increased in breast cancer patients compared to healthy subjects." (PMID 37108425, 2023). "CXCL1 also acts on cancer-associated adipocytes, causing STAT3 activation in them, which leads to the production of LIF which in turn increases CXCL1 production in breast cancer cells." (PMID 37108425, 2023). "CXCL1 expression is higher in inflammatory breast cancer than in other breast cancer subtypes." (PMID 37108425, 2023). "CXCL1 causes the migration of triple-negative MDA-MB-231 breast cancer cells, MCF-7 cells (ER+PR+HER2−), Zr-75-1 cells (ER+PR+HER2+), triple-negative HCC-1937 breast cancer cells, and HER2-positive SKBR3 breast cancer cells (ER−PR−HER2+)." (PMID 37108425, 2023). "Co-culturing lung fibroblasts with human breast cancer increased the secretion of CXCL1 and IL-6." (PMID 36607556, 2023). "We found that chronic psychological stress could enhance TAM/CXCL1 signaling in the breast cancer microenvironment via the GC/GR axis." (PMID 37210553, 2023). "Also important in the induction of breast cancer cell migration by CXCL1 are Akt/protein kinase B (PKB), NF-κB, and STAT3." (PMID 37108425, 2023). "This may be the reason for the higher CXCL1 expression in basal-like triple-negative breast cancer than in other breast cancer subtypes." (PMID 37108425, 2023). "CXCL1 expression in breast cancer cells is also increased by Notch signaling." (PMID 37108425, 2023). "In breast cancer, 7.5% of primary tumors have a CXCL1 gene amplification." (PMID 35054978, 2022). "Interestingly, COX-2, CXCL1, and IL-8 have been identified as critical genes that mediate breast cancer invasion and metastasis to lung and lymph nodes." (PMID 36588678, 2022). "M2 TAMs secrete CXCL1 in breast cancer and promote tumor metastasis." (PMID 35740975, 2022). "In addition, in breast cancer, CXCL1 can attract CD11b+Gr1+ myeloid stromal cell population to the tumor microenvironment, which in turn generates several chemokine members that can serve as paracrine stimulators for the survival of tumor cells." (PMID 35764974, 2022). "The amplification of the CXCL1 gene is observed in 20% cases of breast cancer metastasis." (PMID 35054978, 2022). "Nevertheless, we are the first group, to our knowledge, to analyze the diagnostic utility of CXCL1 and CXCL8 in breast cancer, in combination with CA 15-3, and we hope that our research will inspire other researchers and prove to be useful in the diagnostic process in the future." (PMID 36431173, 2022). "Finally, a variety of chemokines are induced by poly(I:C) exposure, including Ccl2, Ccl5 and Cxcl1 in 4T1 mammary carcinoma cells in a dose-dependent manner." (PMID 35737804, 2022). "Therefore, we believe that breast cancer cells express more CXCL1, CXCL2, CXCL3, and CXCL8 after co-culturing with adipocytes." (PMID 35280694, 2022). "CXCL1, produced by breast cancer cells, can promote cancer growth and development." (PMID 36497164, 2022). "Moreover, we found a positive correlation of HB-EGF and CXCL1 in multiple human tumors, including breast cancer." (PMID 35998057, 2022). "Their results showed that Jinrong granule could inhibit the ability of CXCL-1 to promote the migration and proliferation of breast cancer cells and it could also reverse the promoting effect of CXCL-1 on breast cancer through the CXCL-1- CLCR2/CCL20 pathway." (PMID 34737734, 2021). "A separate study into the oestrogen receptor-positive MCF-7 breast cancer cell line identified a new potential mechanism, CXCL1/2, through which mechanical stimulation of osteocytes may upregulate proliferation and migration in these cells." (PMID 34200761, 2021).
breast carcinoma (continued). "This study not only provides preclinical evidence supporting the application of ADQ in inhibiting breast cancer metastasis but also sheds novel insights into TAM/CXCL1/NF-κB/FOXP3 signaling as a promising therapeutic target for Treg modulation and breast cancer immunotherapy." (PMID 34461944, 2021). "This study not only provides preclinical evidence supporting the clinical use of ADQ in the treatment and prevention of breast cancer metastasis but also highlights TAM/CXCL1/Treg blockage as a promising treatment strategy for breast cancer immune escape and metastasis." (PMID 34461944, 2021). "That is, breast cancer patients with high expression of CXCL1 have a better prognosis, indicating that CXCL1 could be a novel favorable prognostic indicator." (PMID 33959656, 2021). "Meanwhile, CXCL1 knockdown in the co-injected TAMs partially attenuated the promotion effect of TAMs on breast cancer growth, while CXCL1 overexpression in the co-injected TAMs was demonstrated to accelerate breast cancer growth and metastasis in the zebrafish xenotransplantation model." (PMID 34461944, 2021). "Furthermore, the anti-metastatic effects of curcumin in MDA-MB-231 breast cancer cells was correlated with the reduction of inflammatory cytokines CXCL1 and CXCL2 mRNAs and proteins, which are both tightly related to metastases." (PMID 34298639, 2021). "Similarly, both the in vivo imaging assay and HE staining assay suggested that ADQ significantly suppressed breast cancer lung metastasis, which was abrogated by CXCL1 overexpression in co-injected TAMs." (PMID 34461944, 2021). "However, we believe that in breast cancer, CXCL1-2 secreted and recruited by Neutrophils will initially come to the tumor cell area with them, so as to achieve the efficacy of killing tumor cells." (PMID 34123826, 2021). "It is important to further investigate whether TAM/CXCL1 signal could also promote breast cancer metastasis by modulating Treg chemotaxis and differentiation." (PMID 34461944, 2021). "Next, we aimed to investigate whether belinostat treatment could induce the expression of CXCL1 in other breast cancer lines." (PMID 33959656, 2021). "The chemokine C-X-C motif ligand-1 (CXCL1) is involved in BC metastasis, but the question of whether it regulates breast cancer stem cell (BCSC) behavior is yet to be explored." (PMID 34195201, 2021). "In addition, knockdown of CXCL1 in THP-1-dervied macrophages suppressed breast cancer growth and lung metastasis in the orthotopic breast cancer xenografted mice." (PMID 32283687, 2020). "More specifically, we noted that CXCL1 might elevate visfatin levels via a positive feedback loop, with recombinant CXCL1 treatment of breast cancer cells resulting in significantly increased visfatin expression." (PMID 33256011, 2020). "Providing mechanistic insight, microarray-based mRNA profiling of HS578T-tet-off-HEYL human breast cancer cells revealed upregulation of several angiogenic factors including CXCL1/2/3 upon HEYL expression, which was validated by RT-qPCR and protein array analysis." (PMID 33520697, 2020). "Therefore, Runx2 is critical for the CXCL1-induced osteomimetic phenotype by activating the transcription of BRGs in breast cancer cells." (PMID 33123472, 2020). "Moreover, CXCL1 silencing in TAMs was found to inhibit breast cancer growth and lung metastasis via inhibiting NF-κB/SOX4 signaling in both murine and human models." (PMID 32213179, 2020). "However, our previous findings demonstrated that CXCL1 acts as the highest chemokine secreted by TAMs isolated from breast cancer." (PMID 32213179, 2020). "Furthermore, CXCR2 and several of its ligands (CXCL1, CXCL2, CXCL5, CXCL7 and CXCL8) have also been linked to breast cancer progression and metastatic invasion." (PMID 32581213, 2020).
breast carcinoma (continued). "In addition, the inhibition of the IRE1α RNase activity downregulates the expression and secretion of CXCL1 in multiple breast cancer cell lines, indicating the possibility that IRE1α promotes neutrophil recruitment by activating CXCL1." (PMID 32850317, 2020). "Additionally, CXCL1 is abnormally up-regulated in many other cancers, such as colorectal cancer, breast cancer, bladder cancer and epithelial ovarian cancer." (PMID 33223508, 2020). "In this study, we found that XIAOPI formula could inhibit TAMs/CXCL1 signaling, subsequently decline HSPCs activation and differentiation into MDSCs, and finally inhibit breast cancer cell proliferation and metastasis." (PMID 32213179, 2020). "Together, these results indicate that the cross-talk between macrophages and breast cancer cells in the premetastatic niche may be indirectly mediated by CXCL1 triggered by V-THP-1, resulting in breast cancer progression." (PMID 33256011, 2020). "Our study demonstrated that XIAOPI formula could inhibit breast cancer PMN formation by inhibiting TAMs/CXCL1 signaling." (PMID 32213179, 2020). "The present study provides new insights into the adipocytokine, visfatin, and its ability to indirectly influence breast cancer progression through monocytic cell differentiation to TAMs, and trigger cytokine CXCL1 secretion to increase the malignant behavior of breast cancer." (PMID 33256011, 2020). "CXCL1 may act as a prognostic marker for several cancers including breast cancer, and has been correlated with tumor cell survival and metastasis." (PMID 33256011, 2020). "Our previous study suggested that XIAOPI formula could suppress breast cancer growth and lung metastasis via interrupting TAMs/CXCL1 signaling." (PMID 32213179, 2020). "A positive feedback loop may exist, allowing CXCL1 to induce breast cancer cells to express more visfatin." (PMID 33256011, 2020). "Neu+ mammary tumor line secreted G-csf, Ccl-1, Ccl-5, Cxcl-1, Cxcl-2, Cxcl-10, and Il-1ra." (PMID 31941005, 2020). "We also have previously reported that CXCL1 derived from TAMs could promote the epithelial-mesenchymal transition, migration, and invasion of breast cancer cells in vitro." (PMID 31803057, 2019). "Western blot assay further convinced that CXCL1 administration could elevate β-catenin protein expression levels in breast cancer cells while reversing the inhibitory effect of XPS on β-catenin protein expression in the co-cultured breast cancer cells." (PMID 31803057, 2019). "In conclusion, XPS could inhibit breast cancer growth via interrupting CXCL1-mediated interaction between TAMs and CSCs." (PMID 31803057, 2019). "Altogether, XPS could inhibit the self-renewal activity of breast CSCs in the breast cancer cells and TAMs co-culture system by inhibiting TAMs/CXCL1 pathway." (PMID 31803057, 2019). "Taken together, our results indicated that TAMs/CXCL1 promotes breast cancer metastasis via NF-κB/SOX4 activation, and CXCL1-based therapy might become a novel strategy for breast cancer metastasis prevention." (PMID 30158589, 2018). "The results of this study showed that CXCL1 was the most significant cytokine derived from TAMs for inducing breast cancer metastasis, suggesting that the NF-κB/SOX4 pathway may be involved in downstream signaling." (PMID 30158589, 2018). "To determine whether exogenous CXCL1 could promote breast cancer metastasis, we added the CXCL1 cytokine to cells, and found that 0–50 ng/mL CXCL1 had little influence on the cell proliferation of the 4T1, MDA-MB-231 and MCF-7 breast cancer cells." (PMID 30158589, 2018). "Because cancer stem cells (CSCs) are reportedly the root of cancer recurrence and metastasis, we determined if CXCL1 could increase the population of CSCs in breast cancer cells." (PMID 30158589, 2018). "When CXCL1 was overexpressed in breast cancer cells, SOX4 expression was concomitantly increased." (PMID 30158589, 2018).
breast carcinoma (continued). "Western blotting showed that with increasing concentrations of CXCL1, the expression of IKKα (IκB kinase α) and IKKβ and their phosphorylated form p-IKKα/β was upregulated in breast cancer cells, which induced dissociation of IκBα from p65 and led to p65 phosphorylation." (PMID 30158589, 2018). "CXCL1 silencing in TAMs significantly inhibited breast cancer growth and metastasis." (PMID 30158589, 2018). "CXCL1 overexpression primes breast cancer cells for survival in metastatic sites." (PMID 29262555, 2017). "However, further research is still needed to clarify the pathological significance of CXCL-1 in promoting breast cancer metastasis and to identify the potential CXCL-1 inhibitors from the formula via high-throughput screening technique." (PMID 29109519, 2017). "CXCL1/2-CXCR2 axis may involve in breast cancer progression, and Ly6G+CD11b+ cells sorted from tumor tissues express higher levels of CXCR2 than Ly6C+CD11b+ cells, F4/80+ cells and CD31+ cells." (PMID 29383101, 2017). "Evaluation of the mechanism demonstrated that CXCL-1 administration significantly abrogated the metastatic inhibition effects of XIAOPI on breast cancer migration, invasion, stem cells subpopulations, epithelial-mesenchymal transition(EMT), or mammosphere formation abilities." (PMID 29109519, 2017). "CXCL-1 high expression in breast cancer cells could attract CD11b+Gr1+ myeloid cells into the tumor and therefore resulting in chemoresistance and metastasis." (PMID 29109519, 2017). "Our work highlights the role of CXCL-1 as a key target in breast cancer development and in the action of XIAOPI formula and also contributes to the exploration of the mechanism underlying TCM and the promotion of its development in the treatment of complex disease." (PMID 29109519, 2017). "CXCL1 has also been reported to be overexpressed in renal, gastric, skin, and breast cancers." (PMID 27682863, 2016). "In addition, curcumin inhibits breast cancer metastasis by decreasing the inflammatory cytokines, chemokine (C-X-C motif) ligand 1 (CXCL1) and CXCL2." (PMID 27999817, 2016). "While TGF-β and HGF are both co-expressed in the tumor, our studies indicate that low TGF-β concentrations and high HGF concentrations in the local breast cancer stroma may result in increased CXCL1 expression." (PMID 26252654, 2015). "Recent studies have shown that CXCL1/2 can be hyperactivated in breast cancer cell lines by chemotherapy and that blocking CXCR2 in conjunction with chemotherapeutic agents could markedly reduce lung metastases in xenograft-implanted mice." (PMID 26503598, 2015). "Thus, it is possible for stromal CXCL1 protein expression levels to be higher than RNA levels, as observed in breast cancer stroma." (PMID 25344051, 2014). "Given the importance of CXCL1 expression in breast cancer, the goal of this study was to: characterize further the expression patterns of CXCL1 in breast cancer stroma, determine the prognostic significance of stromal CXCL1 expression and identify factors affecting stromal CXCL1 expression." (PMID 25344051, 2014). "To determine whether CXCL1 was expressed in particular fibroblast subsets in breast cancer, we performed co-immunofluorescence staining for CXCL1 expression with α-SMA or FSP1." (PMID 25344051, 2014). "Increased CXCL1 expression in breast cancer stroma correlates with poor patient prognosis." (PMID 25344051, 2014). "CXCL1 is a chemotactic cytokine shown to regulate breast cancer progression and chemo-resistance." (PMID 25344051, 2014). "Blocking CXCL1 signaling improved chemotherapy efficacy by diminishing metastasis in breast cancer." (PMID 24376747, 2013). "CXCL1/2 reportedly mediates breast cancer metastasis and esophageal cancer cell proliferation." (PMID 24376747, 2013).
breast carcinoma (continued). "Finally, we tested whether CXCL8 and CXCL1 expressions correlate with EMT-associated genes, including VIM (gene for Vim), SNAI1 (gene for Snail1), and TWIST1 (gene for Twist1) in breast cancer cell lines using the HMS LINCS dataset." (PMID 40833805, 2025). "Breast cancer cells exhibiting over-activation of IRE1α can stimulate the production of proinflammatory and immunomodulatory cytokines, including IL-6, interleukin-8 (IL-8), C-X-C motif chemokine ligand 1 (CXCL1), and granulocyte-macrophage colony-stimulating factor (GM-CSF)." (PMID 38672455, 2024). "In addition, CXCL1/HMGB1 autophagic axis might be triggered following chemotherapy in breast cancer." (PMID 39394189, 2024). "Targeting CXCL1-mediated autophagy may be one of the MDR reversal mechanisms in breast cancer." (PMID 39394189, 2024). "Clinicopathological studies have suggested that CXCL1 exhibits elevated expression in breast cancer tissue than in normal tissue and is closely correlated with advanced tumour stage, increased recurrence and decreased overall survival in patients with breast cancer." (PMID 39051750, 2024). "Additionally, CXCL1 could facilitate PMN formation in breast cancer and colorectal cancer by recruiting CXCR2+ MDSCs." (PMID 39051750, 2024). "Considering that CXCL1 is among the most abundantly secreted chemokines by TAMs, this phenomenon may arise from the suppression of macrophage infiltration in tumours, given the limited influence of GW4869 treatment on CXCL1 secretion by breast cancer 4T1 cells." (PMID 39051750, 2024). "CXCL1 may also be important in the formation of breast cancer metastasis in other organs." (PMID 37108425, 2023). "Furthermore, flow cytometry results show that the population of CD11b+GR1+-MDSCs in the spleen, lung, and peripheral blood of CXCR2KO mice was significantly reduced, further confirming the crucial role of CXCL1/CXCR2 axis in regulating the bio-functions of MDSCs during breast cancer progression." (PMID 37210553, 2023). "Here, we hypothesized that the N1-to-N2 chemoattractant ratio, such as the Cxcl1-to-S100a8 gene ratio, could be a better biomarker to predict the survival of breast cancer patients than the single gene since the ratio can indicate whether N1 is the dominant neutrophil phenotype in the MNs." (PMID 37553342, 2023). "CXCL1 may also play some role in the formation of lung metastasis in breast cancer." (PMID 37108425, 2023). "Using samples from breast cancer patients, we found that AhR is frequently over-expressed in ER-negative human breast tumors, and this is closely correlated with elevated expression of the NF-кB subunit RelB and inflammatory markers such as IL-8 (CXCL1 in mouse) and COX-2." (PMID 36588678, 2022). "Additionally, ADQ extract could inhibit breast cancer metastasis by inhibiting CXCL1-mediated autophagy." (PMID 34461944, 2021). "CXCL1 may induce visfatin production to form a positive feedback loop, which is supported by the finding that treatment of breast cancer cells with CXCL1 recombinant protein resulted in significantly increased visfatin expression in MCF-7, but not MDA-MB-231 cells." (PMID 33256011, 2020). "Therefore, we focused on the role of CXCL1 in breast cancer cells." (PMID 33256011, 2020). "Additionally, CXCL1 silencing in TAMs could inhibit the growth and lung metastasis of breast cancer xenografts induced by TAMs in vivo." (PMID 31803057, 2019). "Furthermore, both XPS treatment and CXCL1 knockdown in TAMs could partly abrogate the promotion effect of TAMs on mammary tumor growth and breast CSCs population." (PMID 31803057, 2019). "We could prove a direct correlation between the cytokines and miR181b by overexpression or inhibition of miR181b in metastatic breast cancer cells, which had a significant impact on CXCL-1 and -2 expressions and subsequently on metastasis formation in vivo in immunodeficient mice." (PMID 29890744, 2018).